CD40 (CD40 molecule)
Diseases named in the same sentence as CD40 in open-access papers (continued):
Sharing a sentence is not in itself a finding about the gene and the disease.
leukemia (16 papers, 2011 to 2025). A malignant (clonal) hematologic disorder, involving hematopoietic stem cells and characterized by the presence of primitive or atypical myeloid or lymphoid cells in the bone marrow and the blood. "The high levels of CD86 are found in leukemia and leads to inactivation of T cells and relapse risk, whereas, expression of CD40 has diverse effects on cell functions to induce immune response." (PMID 40896706, 2025). "Past observations that CD40 signaling induces survivin in quiescent CLL cells suggested that signaling from proximal T cells was required for its expression in this leukemia." (PMID 39664277, 2024). "In particular, we focused our attention on its potential effect on CCL17, CD40 and PI3KCD mRNAs, which are biologically relevant to CLL, and on DDR1 mRNA that encodes a tyrosine kinase receptor expressed in several tumors and leukemias." (PMID 26305332, 2015). "As for GZMB+ Bregs, we found that BANK1 was decreased in other subtypes of Bregs, including IL10+ and CD24hiCD38hi transitional regulatory B cells, along with BANK1 was down-regulated in activated/differentiated B cells, as in CD40-activated B cells, in leukemia and plasma cells." (PMID 33815360, 2021). "If anti-leukemia T cells are infused remote from transplant or when antigens are restricted to leukemia cells, their efficacy would be enhanced by antigen immunization with anti-CD40 as an adjuvant." (PMID 32839441, 2020). "For example, the combination of GM-CSF, IL-4, and TNFα induced the expression of MHC II, CD40, CD86, CD1a, CD1b, and CD1c by neutrophil-committed precursors isolated from leukemia patients receiving G-CSF treatments." (PMID 24278484, 2013). "This study showed that oncogenic FLT3 regulates proteins involving diverse cellular processes and affects multiple signaling pathways in human leukemia that we previously appreciated, such as Fc epsilon RI-mediated signaling, BCR, and CD40 signaling pathways." (PMID 21552520, 2011). "In the context of deletional CD8+ T cell tolerance mediated by cDC1s, we have shown that targeting cDC1 activation with toll-like receptor (TLR), CD40, or simulator of interferon genes (STING) agonists can be effective in restoring functional anti-leukemia CD8+ T cell responses." (PMID 34758311, 2021). "Additionally, it has been demonstrated that primary leukemia cells secrete CCL22 and CCL17 in response to CD40 ligation, indicating that the chemokines may direct B-cell responses that are dependent on T lymphocytes in secondary lymphoid tissues by enlisting helper T lymphocytes and dendritic cells." (PMID 37259456, 2023). "For instance, it has been reported that THP-1 cells and the CD34 + (KG-1) leukaemia cell line incubated with varying concentrations of rhGM-CSF and rhIL-4 for 5 days showed upregulated levels of CD11c, CD80 and CD86 and of the cell-surface receptors CD40, CD209 (DC-SIGN) but failed to express CD83." (PMID 34800147, 2022).
Crohn disease (15 papers, 2007 to 2025). A gastrointestinal disorder characterized by chronic inflammation involving all layers of the intestinal wall, noncaseating granulomas affecting the intestinal wall and regional lymph nodes, and transmural fibrosis. "In this study, we tested three genes, namely, IL23R, IRF5 and CD40, which have been associated with other immune-mediated diseases, including Crohn's disease (CD), psoriasis, SLE and GD, for an association with type 1 diabetes." (PMID 18045485, 2007). "Seven shared risk genes (CD40, PTPN22, CD226, BATF, PRKCB, RasGRP1, and PTPN2) are involved in cytokine pathways linked to Crohn’s disease." (PMID 40839671, 2025). "In the context of Crohn’s disease, TNFα can show anti-inflammatory activity by down-regulating the CD40/CD40L pathway." (PMID 38256421, 2024). "Overexpression of CD40 is observed in the colonic mucosa of patients affected by Crohn’s disease and ulcerative colitis." (PMID 36558497, 2022). "Yet, remarkably, the surface expression of CD40, a co-stimulatory protein required for antigen presentation, was mainly detectable in Crohn’s disease-derived ASCs." (PMID 33924264, 2021). "Similarly, a clinical study using ch5D12, another antagonistic anti-CD40 antibody, in patients with moderate-to-severe Crohn’s disease showed promising safety and pharmacodynamic profiles." (PMID 41567217, 2025). "In addition, we investigated another anti-CD40 antagonist Abbv-323 (ravagalimab) that has undergone clinical testing in Crohn's disease as an Fc-silent hIgG1." (PMID 32442402, 2020). "Furthermore, the treatment of Crohn’s disease patients with antagonistic CD40 antibody showed beneficial responses and high remission rates." (PMID 30653608, 2019). "Moreover, in patients with Crohn’s disease CD40 is overexpressed on mucosal cells, endothelial cells and DCs." (PMID 30653608, 2019). "Finally, we did not obtain any evidence of an association between type 1 diabetes and IL23R, IRF5 or CD40, all of which have previously been associated with other immune-mediated diseases including, most recently, IL23R in Crohn's disease and in psoriasis." (PMID 18045485, 2007). "It has been reported that the DC costimulatory molecule CD40 can bind to its ligand CD40L which is transiently expressed on T cells under inflammatory conditions and expressed significantly greater in ulcerative colitis and Crohn's disease." (PMID 31582900, 2019).
renal cell carcinoma (15 papers, 2006 to 2025). "Further, we could identify a gene signature in renal cell carcinoma (RCC) that predicts resistance to CD40-mediated cytotoxicity, which was associated with a much lower survival rate in patients of different cohorts." (PMID 40397730, 2025). "The cross-linking of CD40 by CD40 ligand activates different signaling pathways in renal cell carcinoma cells and in particular can influence proliferation and motility thus playing a possible role also in the development of metastasis." (PMID 34445576, 2021). "CD40 crosslinking plays an important role in regulating cell migration, adhesion and proliferation in renal cell carcinoma (RCC)." (PMID 34445576, 2021). "Some studies have confirmed that CD40 is easy to be monitored early and is related to urinary system diseases such as renal cell carcinoma." (PMID 32411234, 2020). "CD40 expression has been demonstrated in normal renal cells and their malignant counterparts (renal cell carcinoma, RCC)." (PMID 31815003, 2019). "Tissue samples from nine different solid tumors (bladder, breast, colon, gastric, head and neck, non-small cell lung cancer (NSCLC), ovarian, pancreatic and renal cell carcinoma), constructed in tissue microarray format, were initially assessed for CD40 expression by QIF." (PMID 36894898, 2023). "It has also been suggested that IL-2/CD40 or IL-15/CD40 combination therapy may be more effective than anti-CD40 alone for the advanced treatment of solid tumors, including renal cell carcinoma." (PMID 32256143, 2020). "CD40 expression is accompanied by CD8 T cell infiltration in renal cell carcinoma, indicating that it may be useful as a biomarker for patient survival." (PMID 32256143, 2020). "CD40 agonists represent today the novel frontier in the treatment of this carcinoma, since CD40 ligation plays an important role also in neo-vascularization of tumors and anti-angiogenesis and immunotherapy represent next-generation approaches in the treatment of renal cell carcinoma." (PMID 34445576, 2021). "Indeed, a preclinical surgical study using the renal cell carcinoma model has shown that anti-CD40 may be successfully combined with IL-2 to orchestrate effective DC and CD8 T cell response against distal tumours." (PMID 25518732, 2014). "We studied renal cell carcinoma (RCC) in comparison to normal (human renal proximal tubule) cells, as a model to better understand the role of CD40 in epithelial cells." (PMID 31815003, 2019).
autoimmune thyroid disease (14 papers, 2010 to 2024). Inflammatory disease of the thyroid gland due to autoimmune responses leading to lymphocytic infiltration of the gland. "In the chronic infection stage, specific targeted mRNAs Cd40 and Cd40lg were upregulated and significantly enriched in pathways associated with immunosuppression, including autoimmune thyroid disease and primary immunodeficiency pathways." (PMID 38229193, 2024). "The CD40 C/T-1 polymorphism was found significantly associated with GD in a meta-analysis of 14 studies (4214 cases and 3851 controls) and 4 studies (623 cases and 774 controls) investigating the association between CD40 C/T-1 gene polymorphism and autoimmune thyroid disease risk." (PMID 28133421, 2017). "Previous studies have found that the CD40/CD40 L system plays important roles in the regulation of the humoral response in autoimmune thyroiditis." (PMID 35996408, 2022). "Of the confirmed non-HLA RA susceptibility loci, only the CD40 and TRAF1/C5 variants have not been reported to be associated with either CeD or T1D although CD40 is associated with autoimmune thyroiditis." (PMID 20854658, 2010). "The genes responsible for autoimmune thyroid diseases could be categorized as either thyroid-specific types (e.g., thyroglobulin and TSH receptor) or immune-modulating types (e.g., Forkhead box P3 (FOXP3), CD25, CD40, CTLA-4, and HLA)." (PMID 29884162, 2018).
colon carcinoma (14 papers, 2006 to 2025). "To investigate stress-induced TAM phenotypes on immunotherapy, we treated colon carcinoma MC38 tumor-bearing mice with a single dose of agonistic anti-CD40 or isotype control antibodies on day 11 (1×anti-CD40) or with repeated doses (3×anti-CD40)." (PMID 41176316, 2025). "In MC38 colon tumors, repeated anti-CD40 or radiotherapy created necrosis that split TAMs into peripheral Cxcl9+ and peri-necrotic Spp1+ subsets." (PMID 41176316, 2025). "Based on previous studies, we found that OK-432, as an adjuvant, was beneficial to the treatment of colon cancer via the CD40/CD40L axis." (PMID 35715855, 2022). "Vorinostat or panobinostat have been shown to present synergistic effects in combination with the immune cell stimulating antibodies anti-CD40 and anti-CD137 in immunocompetent models of mammary, renal and colon carcinoma." (PMID 25669970, 2015). "MC38 cells are immunogenic and exhibit high expression of the co-stimulatory molecules CD40 and CD86 on the surface of dendritic cells compared with CT26 colon cancer cells; thus, PDT is more effective against MC38 tumor-bearing models compared with CT26 or LLC tumor-bearing models." (PMID 37762216, 2023). "One of these is CD40, which was reported to be expressed in 110 human colon cancer tissue samples but not in normal colon tissues and is known to be associated with apoptosis and immune response." (PMID 28878142, 2017).
mesothelioma (14 papers, 2014 to 2024). A usually malignant and aggressive neoplasm of the mesothelium which is often associated with exposure to asbestos. "We have previously shown that intra-tumoral IL-2 combined with anti-CD40 antibody leads to AE17 mesothelioma tumor regression in young mice; this was associated with increased CTL activity." (PMID 30459812, 2018). "These original immunotherapeutic strategies involved the administration to mesothelioma-bearing animals of systemic cytokines, such as recombinant interferon alpha (IFNα) and also activating anti-CD40 antibodies." (PMID 35431929, 2022). "It has been demonstrated that IL-2/CD40 agonist combination therapy results in NK cell infiltration into mesothelioma tumors." (PMID 34686187, 2021). "We have previously shown that local IL-2/anti-CD40 immunotherapy can enhance anti-tumor T cell activity and intra-tumoral inflammation leading to resolution of mesothelioma tumors in young (aged 2–3 months) female C57BL/6J mice." (PMID 30459812, 2018). "We have previously shown that local intra-tumoral administration of IL-2/anti-CD40 immunotherapy induces mesothelioma tumor regression in young (aged 2–3 months) female C57BL/6J mice; mediated primarily by neutrophils, CTLs and macrophages." (PMID 30459812, 2018). "The aim of this study was to examine the influence of aging on DC and T cell function in healthy mice vs. mice with mesothelioma, and to examine responses to IL-2/CD40 immunotherapy in elderly and young mesothelioma-bearing mice." (PMID 30560130, 2018). "Fifteen patients with mesothelioma received up to six 21-day cycles of pemetrexed plus cisplatin chemotherapy and anti-CD40 (CP-870,893)." (PMID 28619093, 2017). "We recently published the results from a phase Ib clinical trial combining the anti-CD40 agonist antibody CP-870,893 with cisplatin/pemetrexed chemotherapy in patients with mesothelioma." (PMID 28619093, 2017). "However, after local IL-2 and/or anti-CD40 antibody treatment of mesothelioma tumors, NK cells help acquire and/or maintain systemic immunity and long-term effector/memory responses." (PMID 36831074, 2023). "However, the results of subsequent preclinical experiments led directly to the establishment of a clinical trial using activating anti-CD40 with chemotherapy in patients with mesothelioma." (PMID 35431929, 2022). "The synergy between gemcitabine and CD40 agonism was observed in murine mesothelioma." (PMID 33804039, 2021). "Collectively, our data suggests that checkpoint blockade of inhibitory molecules may improve responses to IL-2/CD40 immunotherapy in elderly hosts with mesothelioma." (PMID 30560130, 2018). "Using the murine mesothelioma model, we revisited this hypothesis and tested the effect of chemotherapy on neoantigen cross presentation as well as the effect of combination chemotherapy with low dose anti-CD40 therapy." (PMID 35431929, 2022). "Expanding on the theme that CD40 stimulation and PRR stimulation can be additive or synergistic but could be limited by cytokine-mediated toxicity, intratumoral delivery of a TLR7 agonist along with systemic CD40 stimulation has been shown to be effective in a murine model of mesothelioma." (PMID 34282297, 2022). "Our study shows that aging programs development of a suppressive immune environment, which is reflected by DCs and T cells, and this may compromise generation of anti-tumor immune responses, influence mesothelioma progression and responses to IL-2/CD40 immunotherapy." (PMID 30560130, 2018). "The increased regulatory status of elderly DCs and T cells may not only affect tumor progression, but also the efficacy of anti-tumor immunotherapies, which is supported by our data showing that IL-2/CD40 immunotherapy is less effective in inducing mesothelioma regression in elderly mice." (PMID 30560130, 2018).
mesothelioma (continued). "Furthermore, the age-related suppressive status of elderly TDLN CD11c+ cells and T cells was exacerbated during IL-2/CD40 immunotherapy, which may have contributed to its reduced efficacy in elderly mice with mesothelioma." (PMID 30560130, 2018). "Mice were vaccinated with syngeneic bone marrow-derived DCs loaded with either pancreatic cancer (in KPC mice) or mesothelioma (in AE17 mice) lysate and consequently treated with FGK45 as a CD40 agonist." (PMID 36389779, 2022). "Established subcutaneous murine ABA-HA mesothelioma tumors in BALB/c mice were surgically debulked by 75% and treated with either: i) saline; ii) intratumoral IMQ; iii) systemic anti-CD40 antibody, or using a combination of IMQ and anti-CD40." (PMID 25518732, 2014). "Mesothelioma-lysate-loaded DCs combined with CD40 agonist-induced tumor growth reduction and improved survival time rather than anti-CD40 alone." (PMID 36389779, 2022). "CD40 agonism administered before gemcitabine or concurrent with gemcitabine, but not after, resulted in lethal toxicity in murine mesothelioma and KPC mice as an effect of macrophage activation." (PMID 33804039, 2021). "Therefore, to address this issue we examined the role of macrophages in young (3 months) vs. elderly (20–24 months) mesothelioma-bearing female C57BL/6J mice during tumor growth and following treatment with intra-tumoral IL-2/anti-CD40 immunotherapy." (PMID 30459812, 2018).
Arthritis (13 papers, 2006 to 2022). Inflammation of a joint. "As CD40-CD40L interactions have been implicated in arthritis a reduction in CD40 expression due to STAT-1 decoy ODN application may explain the attenuated arthritic symptoms in our AIA model." (PMID 16507120, 2006). "Among 35 MD-associated genes with drug-interaction data, four MD-specific genes interacted with drugs associated with arthritis: NR3C1 (N = 6), NRG1 (N = 2), CD40 (N = 2), TYR (N = 1)." (PMID 34603368, 2021). "CD40 polymorphisms are also associated with SLE clinical manifestation, mainly nephritis and arthritis." (PMID 26474561, 2015). "The interaction of CD40 and CD154 has been implicated in a number of diseases such as arthritis, cancer, atherosclerosis, lupus nephritis, and acute or chronic graft-versus-host disease." (PMID 23300544, 2012). "Agonistic monoclonal antibodies to CD40 reduced collagen-induced arthritis, possibly through upregulation of IL-10 and to lesser extent IL-4, indicating an anti-inflammatory role in addition to the pro-inflammatory role of CD40." (PMID 23300544, 2012). "Mice with collagen II (CII)-induced arthritis (CIA) were administered siRNA targeting the CD40 molecule." (PMID 20102615, 2010). "The transcription factor STAT-1 (signal transducer and activator of transcription-1) plays a pivotal role in the expression of inflammatory gene products involved in the pathogenesis of arthritis such as various cytokines and the CD40/CD40 ligand (CD40/CD40L) receptor-ligand dyad." (PMID 16507120, 2006). "Our experiments demonstrate that a single local application of a decoy ODN neutralizing the transcription factor STAT-1 effectively inhibits antigen-induced arthritis, most likely through attenuating the enhanced expression of CD40 and other effector molecules in macrophages." (PMID 16507120, 2006). "The beneficial effects of the STAT-1 decoy ODN in experimental arthritis presumably mediated in part by affecting CD40 signalling in macrophages may provide the basis for a novel treatment of human RA." (PMID 16507120, 2006). "When treating complete Freund’s adjuvant-induced arthritis, AG inhibits a series of molecules related to arthritis, such as cyclooxygenase-2 (COX-2), NF-κB, p-p38, CD40, TNF-α, IL-1β, and IL-6." (PMID 36188549, 2022). "Andrographolide treated CFA-induced arthritis by inhibiting the expression of a series of arthritis-related molecules, including COX-2, NF-κB, p-p38, CD40, TNF-α, IL-1β, and IL-6." (PMID 36238575, 2022). "CD40 was also expressed in the cartilage of all monkeys with induced arthritis, but not in healthy controls in which RA was not induced." (PMID 29391506, 2018). "In this study, CD40 was expressed on the cartilage in all of the monkeys with induced arthritis, but not in healthy controls in which RA was not induced." (PMID 29391506, 2018). "Inhibition of arthritis clinical score was observed in the mice treated with CD40 siRNA, as opposed to control siRNA-treated mice which exhibited no inhibition." (PMID 20102615, 2010). "Both the neutralizing anti-CD40 monoclonal antibodies and the non-antibody scaffold protein VIB4920 (a human CD40L inhibitor) have been shown to inhibit CIA development by reversing arthritis and blocking immune cells from accessing synovial tissue." (PMID 34440629, 2021).